RNU6-1292P (RNA, U6 small nuclear 1292, pseudogene)
Gene: Small nuclear RNA gene on chromosome 11 (85,509,938 to 85,510,044, forward strand). Ensembl gene ENSG00000206583.
Homologues: Orthologues: chimpanzee U6 (98% identical), rabbit U6 (79% identical), rabbit U6 (74% identical), mouse Gm23219 (64% identical). Paralogues in human: RNU6-21P (88% identical), RNU6-641P (88% identical), RNU6-1270P (87% identical), RNU6-949P (87% identical), RNU6-128P (86% identical), RNU6-33P (86% identical), RNU6-698P (86% identical), RNU6-1 (85% identical), RNU6-1060P (85% identical), RNU6-116P (85% identical), RNU6-15P (85% identical), RNU6-19P (85% identical), and 1287 more.